CTLA4 (cytotoxic T-lymphocyte associated protein 4)
Diseases named in the same sentence as CTLA4 in open-access papers (continued):
Sharing a sentence is not in itself a finding about the gene and the disease.
tumor (continued). "In addition, we noticed that the expression of LAG3 and GZMK is higher than that of immune inhibitors, such as PD-L1, TIM3, and CTLA4, in the CD8+ T_3 cluster; thus, LAG3 or GZMK may be a better target for tumor immunotherapy in ccRCC." (PMID 35812372, 2022). "Furthermore, we discovered that L1CAM was linked to immune cell infiltration and ICG (CD274, LAG3, PDCD1LG2, CTLA4), and we hypothesized that L1CAM may have a regulatory role in the tumor microenvironment, influencing tumor growth and metastasis." (PMID 36212450, 2022). "Pro-inflammatory cytokines produced by TAMs could trigger the accumulation and expansion of CD4+ Th17 cells to foster angiogenesis and overexpressing CTLA-4, programmed death-1 (PD-1), and glucocorticoid-induced tumor necrosis factor receptor (GITR), thereby promoting tumor development." (PMID 36168626, 2022). "A study showed that tumor-infiltrating CD8+ cytotoxic T-cells in AML had upregulated inhibitory receptors such as programmed cell death 1 (PD-1), cytotoxic T-lymphocyte antigen 4 (CTLA-4), T-cell immunoglobulin and mucin domain-containing protein 3 (TIM-3), and lymphocyte-activation gene 3 (LAG3)." (PMID 35601490, 2022). "In several pre-clinical mouse models (B16/F10, RENCA and MC38), Tregs in irradiated tumours expressed higher levels of cytotoxic T-lymphocyte-associated antigen-4 (CTLA-4), 4-1BB (CD137, tumour necrosis factor receptor superfamily 9) and Helios compared with Tregs in non-irradiated tumours." (PMID 36106115, 2022). "Besides, C1QTNF6 is obviously correlated with many immune checkpoints including LAG3, PDCD1, CTLA4, which suggested that C1QTNF6 may act as a new immune checkpoint for tumor immunity." (PMID 35401204, 2022). "Molecular characterization of tumor-TME interactions led to the introduction of novel anti-cancer therapies targeting specific components of the TME, such as immune checkpoint blockers (ICB) (i.e., anti-programmed death 1, anti-PD1; anti-Cytotoxic T-Lymphocyte Antigen 4, anti-CTLA4)." (PMID 36077813, 2022). "Therefore, these novel anti-PD-L1 and anti-CTLA-4 mAbs could be useful, especially against tumors with reduced expression of MHC complex, where NK cells could serve as the main players in anti-tumor response, since T cells activity might be impaired." (PMID 36358708, 2022). "Besides, the data on immune checkpoints (such as CTLA4), which potentially attenuate anti-tumoral immune responses and facilitate tumor growth and metastasis, were absent in our study since there were only a few cases treated with CTLA4 in our center." (PMID 35875064, 2022). "Examination of the frequencies of specific myeloid populations in tumor tissue surprisingly revealed significantly lower levels of macrophages (CD45+CD11b+F4/80+) and DCs (CD45+CD11c+) in tumors from the mice that were concomitantly treated with TTFields and anti-PD-1/anti-CTLA-4." (PMID 36430552, 2022). "A comparison with histologic parameters and PD-L1 status revealed significantly higher rates of CTLA-4+ cells in tumors with low pT category (p < 0.0001), absent lymph node metastases (p = 0.0031), and PD-L1 expression in tumor cells or inflammatory cells (p < 0.0001 each)." (PMID 35091676, 2022). "The excellent tumor-killing effect of ICG-PDT in vitro provided us with inspiration to carry out a series of in vivo studies on mice with subcutaneous transplanted MC38 or CT26 cells to investigate the anti-tumor effect of ICG-PDT and the potential combination with CTLA4 antibody." (PMID 35974207, 2022). "A number of studies demonstrated that prolonged exposures to CTLA-4 inhibitors might not be necessary for sustained anti-tumor effects." (PMID 36005172, 2022). "Just as CTLA4 antagonists alone can only restore PD-1+CTLA-4+ TILs response to tumor antigens, but not CTLA4- TILs, single immune checkpoint blockade targets a limited subset of CD8+T cells, while dual or multiple immunotherapies lead to progressively better outcomes." (PMID 36618420, 2022).
tumor (continued). "Similarly, the absence of CD155 exerted an inhibitory effect on tumor growth and metastasis, and blocking of PD-1 or PD-1 and CTLA4 was found to be more effective in the absence of CD155." (PMID 36309698, 2022). "Thus, novel immunotherapeutic strategies aimed at blocking the interaction of PD-1 and CTLA-4 with their ligands, paralleled by the targeting of HLA-G/ILT2 interaction, may greatly enhance the rescue of anti-tumor immune response." (PMID 35328349, 2022). "In addition, unlike the case for IL-15/PD-1 blockade, mice treated with OMCPmutIL-2 in combination with anti–CTLA-4 remained resistant to tumor rechallenge without additional treatment, suggesting long-term immunity." (PMID 35603788, 2022). "Therefore, we showed that non-Fc-containing CTLA-4 VHH retained the ability to induce robust anti-tumor activity in preclinical tumor models." (PMID 35237846, 2022). "Furthermore, MXRA8 was linked to the expression of several immune checkpoints in our work, including PD-1, PD-L1, PD-L2, CTLA-4, TIM-3, and LAG-3; thus, MXRA8 may be involved in tumor immune escape." (PMID 36703779, 2022). "Therefore, in future clinical studies, considering neoadjuvant therapy modalities and CTLA-4/CD86 expression during ICIs, combination therapy might effectively block more immune-evasive tumor mechanisms." (PMID 36428666, 2022). "In addition, the CTLA-4 antibody, which combines with dendritic cells, can decrease the level of CD4+ regulatory T cells (Tregs) and increase the concentration of cytotoxic T cells in metastatic OS mice for tumor suppression." (PMID 36311748, 2022). "Anti-PD-1 × CTLA-4 BsAbs, including AK104,156 MEDI5752,157 and MGD019,158 are expected to synergistically inhibit checkpoint signaling pathways in PD-1/CTLA-4 double-positive tumor-infiltrated lymphocytes (TILs) while enhancing PD-1 degradation and CTLA-4 inhibition in the TME." (PMID 35132063, 2022). "Interestingly, we found that ABZ treatment significantly decreased the tumor PD-L1 level but did not affect the levels of PD-1 and CTLA-4 on CD8+ T cells." (PMID 35577504, 2022). "However, as with the KPA model, co-treatment with anti-PD-1and anti-CTLA-4 failed to control tumour growth." (PMID 35930804, 2022). "Indeed, preclinical models targeting IDO1 strongly enhanced B16 and 4T1 tumor response to both anti-CTLA4 and anti–PD-1 therapy, and demonstrated efficacy regardless of tumor IDO1 expression." (PMID 35040434, 2022). "KD or its principal ketone body, 3-hydroxybutyrate (3HB), induced T cell-dependent tumor growth retardation in melanoma models and reestablished the therapeutic responses in conditions under which anti-PD-1 alone or in combination with anti-CTLA-4 failed to reduce tumor growth." (PMID 35330159, 2022). "Upregulation of immune checkpoint proteins, such as PD-1, CTLA-4, and T-cell immunoglobulin mucin-3 (TIM-3), and of transcripts IL8 and CXCL12, concomitant with downregulation of granzyme B and perforin in tumor MAIT cells, indicates that MAIT cells are exhausted and pro-tumor in HCC." (PMID 36551916, 2022). "Unlike the ligand of CTLA4, one of PD-1’s ligands known as programmed death- ligand 1 (PD-L1), is broadly overexpressed on tumor cells and infiltrating leukocytes; this allows for the induction of PD-1 mediated T cell exhaustion by tumor cells." (PMID 36159789, 2022). "Previous researches revealed that Treg cells were recruited into the human tumor microenvironment and inhibited T cell immunity to abolish the therapeutic efficacy of PD-L1, CTLA-4, and the TGF-β blockade, regardless of whether they were live or apoptotic." (PMID 35646872, 2022). "However, the advantage of Pulsed radiation + anti-CTLA-4 over one cycle of XRT + anti-CTLA-4 group on the secondary tumor growth was not as evident as the primary tumor (Parental: p = 0.0548, Resistant: p < 0.0001)." (PMID 36275767, 2022).
tumor (continued). "The expression levels of the checkpoint inhibitory molecule PD-1, the cell activation marker CTLA-4, the cytotoxic molecule granzyme B, and the cell proliferation marker Ki-67 by tumor infiltrating and splenic CD8+ and CD4+ T cells were not different between the groups." (PMID 35514996, 2022). "Anti-CTLA-4 antibody binds to CTLA-4 on activated T cells and prevents T cell inactivation in lymph nodes during the initial stage of cancer-immunity cycles, while anti-PD-1/PD-L1 antibodies inhibit T cell inactivation in tumor tissue during the effector phase." (PMID 35205802, 2022). "However, importantly, within the CD4-NFAT5-KO transgenic mice, compared to no treatment, treatment with anti-CTLA4 significantly reduced the tumor progression kinetics in all three salt modified diet cohorts." (PMID 35741331, 2022). "Thus, we found that different syngeneic tumor models exhibited differential response to anti-CTLA-4 therapy in the presence or absence of Fc-effector functions." (PMID 35237846, 2022). "Also, to overcome an immunosuppressive TME, several studies suggested that the combination of monoclonal antibodies inhibiting immune checkpoints such as PD-1 or CTLA-4 and CAR-T cell therapy might result in improved anti-tumor activity." (PMID 35720364, 2022). "Immune checkpoint inhibitors, such as anti-PD1 or anti-CTLA4 antibodies, usually block the inhibitory signalings in T cells, or deplete immunosuppressive cells, such as regulatory T cells, and therefore activate T effectors, such as CD8+ T cell, to inhibit tumor progression." (PMID 36008793, 2022). "Similarly, using the same models anti-Ly6G depletion was shown to improve tumor control following anti-CTLA-4 treatment in T-cell inflamed MOC1 tumors, but again not in non-T-cell inflamed MOC2 tumors." (PMID 35937775, 2022). "All T cell subsets and their respective cytokines play essential roles in tumor immunity, and major cancer-killing role of T lymphocytes has made them the target of the majority of immunotherapies such as CAR-T (chimeric antigen receptor) cell therapy and ICIs that target PD-1 and CTLA-4 on T cells." (PMID 36072595, 2022). "In conclusion, combination treatment with anti-CTLA-4 mAb and MUC1 mRNA nanovaccine could increase the infiltration of CD8+ T cells into tumor sites and enhance anti-tumor cytotoxic T-lymphocyte activity by reducing immunosuppressive TME and inhibiting tumor-promoting STAT3 signaling pathway." (PMID 34875483, 2022). "We therefore sought to enhance the tumor-killing activity of DC-CIK cells in two distinct ways: First, by promoting maturation and activation of antigen-presenting DCs through CD40 ligation, and second, by suppressing inhibitory signaling in the effector cells or reducing Tregs by CTLA-4 blockade." (PMID 36091050, 2022). "However, none of them evaluated the effect of tumor antigen loading on DCs as well as CTLA-4 inhibition in them concomitantly." (PMID 35979362, 2022). "Similarly to tumor-infiltrating T cells, splenic CD8+ and CD4+ T cells in mice treated with the combination of AHCC® and DICB had increased expression of Ki-67 and CTLA-4 while granzyme B expression in splenic CD8+ and CD4+ T cells were barely detected by flow cytometry." (PMID 35514996, 2022). "However, this evidence suggests that anti-tumor activity induced by anti-CTLA-4 is not mediated by inhibiting CD80/86-CTLA-4 interactions." (PMID 35326731, 2022). "It is not known whether anti-CTLA-4 can metabolically interconvert the phenotype of Tregs and Th17 cells and how this plays a role in anti-tumor immunity." (PMID 35326731, 2022). "Besides that, expression of TSPAN9 held a significantly negative correlation with tumor immunocyte infiltration as well as immune checkpoint CTLA4." (PMID 35600044, 2022). "In addition, CTLA-4 is expressed by Tregs, and therapeutic anti-CTLA-4 antibodies may also promote anti-tumor immunity by depleting Tregs and abrogating their immunosuppressive functions." (PMID 36497422, 2022).
tumor (continued). "Due to their competition for binding to the ligands CD80 and CD86 and their antagonistic function in the control of the immune system, one could claim that the ratio of expression levels between CTLA-4 and CD28 in the tumor shifts towards CTLA-4, which would result in a higher CTLA-4/CD28 quotient." (PMID 35406584, 2022). "These pioneering studies on the balance between Teffs and Tregs suggest that an increased number of tumor-infiltrating Teffs, rather than the depletion of Tregs may be used to predict sensitivity to anti-CTLA-4 immunotherapy." (PMID 36142818, 2022). "Furthermore, anti-CTLA4, another ICB agent, and RT enhanced CD8+ T cell infiltration in vivo and tumour growth could be controlled more effectively using both treatments than each treatment alone by inducing ferroptosis—a type of programmed cell death." (PMID 36476325, 2022). "Following the accomplishments of PD-1 and CTLA-4 inhibitors, others targeting TIGIT, Tim-3, Lag3 and NKG2A are currently being explored in some solid tumors in various pre-clinical and clinical trials, in order to promote effective anti-tumor immunity with clinical benefits." (PMID 36077799, 2022). "Of note, no NK cell-mediated ADCC was found against other CTLA-4+ T cells, suggesting that other tumor-specific factors might play a role in the selectivity of this process." (PMID 33572396, 2021). "Moreover, modern immunotherapies have been recently developed which target against PD-1, PD-L1, or CTLA-4, which disable the ability of tumor cells to evade the immune system without any significant side effects, especially in mRCC." (PMID 33913471, 2021). "In addition, PD1, CTLA4, LAG3, TIM3 and GZMB were common inhibitory receptors (IRs) in the tumor microenvironment, which could inhibit immune responses and even cause immune escape or tolerance after binding with corresponding ligands." (PMID 34721537, 2021). "McCoy and coworkers confirmed that Bifidobacterium pseudolongum and Lactobacillus johnsonii could significantly enhance the CD8+ T cell responses in the tumor microenvironment (TME) consistent with the improved efficacy of anti-PD-L1 and anti-CTLA-4 therapy on colorectal cancer." (PMID 34439144, 2021). "Furthermore, studies have shown that tumors with MMR defects can also contain other DNA repair defects, such as POLD or POLE mutations, and several immune checkpoint ligands, including PD-1, PD-L1, CTLA-4, LAG-3 and IDO, are also highly expressed in the tumor microenvironment of these patients." (PMID 33968789, 2021). "Moreover, in ICOS- or ICOS ligand (ICOSL)-deficient mice, the efficacy of anti–CTLA-4 therapy was significantly diminished, although the specific contribution of ICOS+CD4+ cells versus ICOS+CD8+ cells in tumor rejection was not addressed in this study." (PMID 33777008, 2021). "Moreover, we analyzed the correlation among four-gene signature (FeSig) (BID, TAZ, MT1G, and SLC7A11), downstream hub genes (CPNE7, WNT10B, ADAMTS14, and RUFY4), and immune checkpoints (PD-1, CTLA4, LAG3, and TIGIT) to further discover potential molecular mechanisms of tumor immunity." (PMID 34367965, 2021). "The treatment with [177Lu]Lu-DOTA-folate or an anti-CTLA-4 antibody had only a minor effect on NF9006 tumor growth and did not substantially increase the median survival time of mice (23 day and 19 days, respectively) as compared with untreated controls (12 days)." (PMID 33078260, 2021). "Using the same OS mouse model, Takenada and colleagues showed that the combination of high-dose local radiation and anti-CTLA4 antibody administration is able to halt tumor growth not only of the treated lesion, but also of a contralateral, untreated tumor (abscopal effect)." (PMID 34359840, 2021).
tumor (continued). "Radiation can activate a type 1 interferon (IFN1) response in tumor cells, and in preclinical studies this has been shown to be critical to the role of radiation in activating an anti-tumor immune response in combination with immune checkpoint inhibition (ICI, eg. anti-CTLA-4, anti-PD-1/PD-L1) 1-10." (PMID 33995649, 2021). "In addition, treating this mixture of immune cells with the immune checkpoint inhibitors (anti-CTLA4 and anti-PD1), which allow for downregulation of Tregs, proper activation of CTL, Th, and memory T cells, with subsequent suppression of tumor cells through downregulation of CD133, CD34, and CD44." (PMID 37305162, 2021). "Moreover, we found that POLE expression in cancers significantly correlated with an immunosuppressive tumor microenvironment, higher intratumoral heterogeneity, and expression of immune checkpoint genes PDCD1, CTLA4, and CD86, possibly mediated via the JAK/STAT and Notch signaling pathways." (PMID 34950188, 2021). "Remarkably, monotherapy with anti-CTLA-4 mAb did not result in suppression of tumor growth." (PMID 34006895, 2021). "Notably, sole application of the anti-CTLA-4, anti-PD-1, and/or anti-HSP90 molecules used either alone or in combination with each other did not markedly impact on the numbers of Treg and T17 lymphocytes recovered from the tumorous tissues." (PMID 34208396, 2021). "However, in advanced tumor stages, when cancer cells engage T cell checkpoints including PD-1 and CTLA4, stimulation of GITR might be disadvantageous for the tumor, as stimulation of GITR also inhibits the suppressive properties on regulatory T cells." (PMID 33538861, 2021). "In addition, we also verified four hub genes (CTLA4, CDSN, ACTN2, and MYH11) that their expression levels in tumor tissue might be regulated by the mechanism of DNA methylation." (PMID 35096593, 2021). "Also, XmAb®22841 (a bispecific antibody that simultaneously targets immune checkpoint receptors CTLA-4 and LAG-3 to promote tumor-selective T-cell activation) has been evaluated in the DUET-4 trial in combination with pembrolizumab (ClinicalTrials.gov Identifier: NCT03849469)." (PMID 34063238, 2021). "We found that CD274 and CTLA4 show significantly higher expression in the TNFSF10high group than in the TNFSF10low group; however, PD-L1 (CD274) was predominantly expressed by tumors while CTLA4 and LAG3 were mostly expressed by T cells in the tumor microenvironment." (PMID 34167551, 2021). "In-depth mechanism studies on tumor immune microenvironment (TIME) of hot tumors have reported that immunosuppressive factors in hot tumors are involved in a negative feedback loop driven by TILs, such as the up-regulation of PD-L1, CTLA-4, and IDO, which are rarely found in TIL-lack cold tumors." (PMID 34138315, 2021). "However, these combined blockades did not outperform the anti-tumor effect of CTLA-4 blockade, suggesting that CTLA-4-mediated immunosuppression does not cause resistance to PD-L1 blockade." (PMID 33923750, 2021). "Special focus should be placed on the triple combination of anti-PD-1/L1, anti-CTLA-4, and anti-VEGF, as this combination has the broadest possible blockade out of all currently established HCC treatment options and thus potentially strongest synergism and anti-tumor effect." (PMID 33919570, 2021). "Combinatorial administration of anti-CTLA-4 with IL-2Cx, a complex of IL-2/anti-IL-2 which directs IL-2 to NK and CD8+ T cells but not Tregs, or IL-15/IL-15Ralpha complexes further tips the tumoral effector/regulatory cell ratio in favor of activated NK cells and enhances tumor control." (PMID 33995422, 2021). "Theresults showed that 120 h ofstimulation with tumor cells (HepG2) significantly promoted the proliferation of CFSE-labeled DC-CIK cells in the DC-CIK + Nb36 group, promoting it far more than in the DC-CIK (p < 0.001) and DC-CIK + CTLA-4 mAb (p < 0.05) groups." (PMID 34525966, 2021).